AGT (angiotensinogen)
Diseases named in the same sentence as AGT in open-access papers (continued):
Sharing a sentence is not in itself a finding about the gene and the disease.
type 1 diabetes (46 papers, 2009 to 2025). "We investigated urinary AGT levels as a candidate marker of the activation of the RAS in type 1 diabetes." (PMID 40003909, 2025). "In contrast, in patients with type 1 diabetes, treatment with empagliflozin significantly increased the urinary AGT/creatinine ratio." (PMID 30717173, 2019). "In pre-albuminuric patients with type 1 diabetes, urinary angiotensinogen levels were already higher than in control subjects." (PMID 29600408, 2018). "Others and we previously reported that an increase in urinary AGT is observed in normoalbuminuric children with type 1 diabetes." (PMID 26380312, 2015). "Urinary AGT excretion is higher in patients with type 1 diabetes compared with control subjects." (PMID 40003909, 2025). "In addition, we reported that an increase in urinary AGT precedes an increase in urinary Alb in experimental type 1 diabetes." (PMID 26380312, 2015). "Urine angiotensinogen, matrix metalloproteinase‐7, and gremlin‐1 concentrations are markedly elevated in people with type 1 diabetes and kidney disease, compared with those with recently diagnosed type 1 diabetes or longstanding type 1 diabetes without kidney disease." (PMID 24793984, 2014). "Median urine AGT/Cr (AGT concentration normalized to urine creatinine) in cases (226.0 ng/mg) was significantly different from those in controls (13.0 ng/mg) and participants with new‐onset type 1 diabetes (8.7 ng/mg)." (PMID 24793984, 2014). "Furthermore, we confirmed the results of the increased urinary AGT levels using rodent models such as streptozotocin-induced type 1 diabetic mice, db/db type 2 diabetic mice, and ZDF type 2 diabetic rats." (PMID 24284398, 2013). "In contrast, in patients with type 1 diabetes and obese rats fed a high-salt diet, SGLT2 inhibition increased urinary AGT levels." (PMID 35710133, 2022). "A protein similar to albumin, namely the urinary angiotensinogen (AGT), has shown very interesting and promising results as early markers of disease severity in type 1 diabetes." (PMID 35628528, 2022). "We find that urine concentration of AGT, MMP‐7, and gremlin‐1 is low at the onset of type 1 diabetes and remains low in people who have intact kidney function after 30 or more years of type 1 diabetes." (PMID 24793984, 2014). "On the other hand, treatment with SGLT2 inhibitors did not alter renal AGT expression in a mouse model of type 1 diabetes." (PMID 35710133, 2022). "Indeed, Cherney et al17 reported that urinary total angiotensinogen excretion, which represents local RAS activity in the kidney, 19 significantly increased owing to treatment with SGLT2 inhibitors in patients with type 1 diabetes mellitus." (PMID 28596160, 2017). "The excretion of urinary angiotensinogen could be a potential biomarker of intrarenal RAS status in clinical and experimental type 1 diabetes." (PMID 24880819, 2014). "Median (IQR) urine AGT concentrations were 226.0 (82.1, 550.3) and 13.0 (7.8, 20.0) μg/g creatinine in type 1 diabetes with and without DKD, respectively (P < 0.001)." (PMID 24793984, 2014). "Furthermore, the finding of low urinary concentration of AGT, gremlin‐1, and MMP‐7 in new‐onset type 1 diabetes establishes a starting point for the trajectory of concentration of these proteins in the time course of DKD." (PMID 24793984, 2014). "We previously examined whether increased urinary AGT excretion is present prior to the onset of urinary albumin in streptozotocin-induced type 1 diabetic mice; we found that urinary AGT may be useful as an early biomarker of the activation of the RAS in experimental type 1 diabetes." (PMID 40003909, 2025). "However, urine AGT concentration has not been reported in type 1 diabetes with kidney disease." (PMID 24793984, 2014). "Creatinine‐adjusted urine AGT was 17‐fold higher with DKD than without DKD and 26‐fold higher than urine AGT concentration at the onset of type 1 diabetes." (PMID 24793984, 2014).
type 1 diabetes (continued). "We measured urine AGT, gremlin‐1, and MMP‐7 in individuals with type 1 diabetes and prevalent DKD (n = 20) or longstanding (n = 61) or new‐onset (n = 10) type 1 diabetes without DKD." (PMID 24793984, 2014). "Treatment with empagliflozin attenuated hyperfiltration in 37 people with type I diabetes not on RAS inhibition and resulted in an increase in urinary levels of angiotensinogen, ACE, ACE-2, rise in plasma angiotensin I, II and renin activity as well as a fall in plasma ACE activity." (PMID 36247425, 2022). "The primary finding of this study is that urine AGT, MMP‐7, and gremlin‐1 concentration are markedly elevated in people with type 1 diabetes and DKD, compared with those with recently diagnosed type 1 diabetes or those with longstanding type 1 diabetes without DKD." (PMID 24793984, 2014).
hypertensive nephropathy (44 papers, 2012 to 2025). Kidney damage that results from chronically elevated blood pressure; complications include glomerular damage resulting in proteinuria and hematuria. "Instead, it has been reported that urinary AGT (UAGT) level correlates with intrarenal AGT and AngII levels in rodent models of hypertensive nephropathy." (PMID 36139118, 2022).
Cognitive impairment (42 papers, 2008 to 2026). Abnormal cognition is characterized by deficits in thinking, reasoning, or remembering. "Evidence has suggested that, in certain instances, the pro-renin binds with the pro-renin receptors instead of binding to renin, leading to angiotensinogen cleavage and overactivation of angiotensin receptors, causing cognitive impairment." (PMID 34827667, 2021). "The levels of angiotensinogen (AGT) is increased in the cerebrospinal fluid of patients with mild cognitive impairment and AD." (PMID 35401145, 2022). "The aim of the presented research was to establish the impact of several polymorphisms in RAS—in the genes of angiotensinogen, ACE, AT1R, and AT2R—on the risk of mild cognitive impairment (MCI) or dementia in PD." (PMID 34302265, 2021).
Hyperinsulinemia (41 papers, 2004 to 2025). An increased concentration of insulin in the blood. "Hyperinsulinism can also increase angiotensinogen synthesis, leading to higher levels of angiotensin II." (PMID 41007785, 2025). "Chronic hyperinsulinemia can lead to increased angiotensinogen production and upregulated expression of the angiotensin II receptor in adipose tissue, further promoting the generation of ROS in tissues such as the myocardium." (PMID 37993858, 2023). "Secondly, IR leads to adverse activation of the sympathetic nervous system, with chronic hyperinsulinemia increasing angiotensinogen release from adipose tissues and angiotensin II receptor expression, ultimately leading to aberrant cardiac remodeling and cardiac dysfunction." (PMID 38027163, 2023). "Obese subjects usually have increases in plasma renin activity, angiotensinogen, angiotensin-converting enzyme activity, and circulating AngII, which trigger or promote renal damage by renal hemodynamic changes and nonhemodynamic pathways such as hyperinsulinemia, oxidative stress, and inflammation." (PMID 22567283, 2012).
renal failure (41 papers, 2009 to 2025). "Unravelling the mechanisms involving intrarenal RAS activation in ADPKD is beyond the scope of this study since this study aims to investigate the clinical usefulness of urinary AGT/Cr as a biomarker of renal insufficiency." (PMID 26092580, 2015). "We presume that CG200745 may not cause renal insufficiency because CG200745 works by inhibiting over-production of angiotensinogen or Ang II in response to HFD not by random inhibition of existing angiotensinogen or Ang II." (PMID 31655853, 2020).
myocardial ischemia (40 papers, 2009 to 2025). A disorder of cardiac function caused by insufficient blood flow to the muscle tissue of the heart. "Myocardial ischemia induces activation of various components of the renin-angiotensin system (RAS), including angiotensinogen, renin, angiotensin-converting enzyme, angiotensins, and angiotensin receptors, in the acute phase of MI and in the postinfarction remodeling process." (PMID 23997803, 2013).
diabetic cardiomyopathy (36 papers, 2010 to 2025). Diabetic cardiomyopathy is a disorder of the heart muscle in people with diabetes. "Angiotensinogen, renin, Ang-I and Ang-II are important in diabetic cardiomyopathy." (PMID 23690953, 2013).
Anxiety (30 papers, 2010 to 2026). Intense feelings of nervousness, tension, or panic often arise in response to interpersonal stresses. "were the first time to describe transgenic rats with low brain angiotensinogen behavioral phenotype as characterized by increased anxiety-related behaviors." (PMID 36761172, 2022). "Subsequently, studies showed low angiotensinogen concentration in the brain leads to anxiety-like behaviors accompanied by a depression-like state." (PMID 36761172, 2022). "A study using TGR (ASrAOGEN) 680 rats, which exhibit reduced levels of AGT in the brain and an anxiety-like or depression-like phenotype, showed that 5-HT and its metabolite 5-HIAA were reduced in brain regions that control emotion, such as the hippocampus and prefrontal cortex." (PMID 37312182, 2023). "After adjusting for confounders, this population based study revealed a lack of association between AGT M235T genotype and heart rate in men and women when analyzed in the absence of data on anxiety." (PMID 20967221, 2010).
dilated cardiomyopathy (30 papers, 2012 to 2026). Cardiomyopathy which is characterized by dilation and contractile dysfunction of the left and right ventricles. "Limited evidence exists for an association between dilated cardiomyopathy (DCM) and the angiotensin-converting enzyme (ACE) gene with an insertion/deletion (I/D) angiotensinogen (AGT) M235T gene polymorphism." (PMID 41209135, 2025).
portal hypertension (30 papers, 2001 to 2025). Increased blood pressure in the portal venous system. "Angiotensinogen is part of a superfamily of serine protease inhibitors (serpins), which include other molecules implicated in liver disease such as alpha-1 antitrypsin and alpha-1 antichymotrypsin." (PMID 38891995, 2024).
ischemic stroke (28 papers, 2010 to 2025). A stroke disorder caused by obstruction of blood flow to the brain, due to thrombotic (local blood clot formation) or embolic (due to a blood clot or other material traveling from another site) event. "The polymorphisms associated with an increased risk of ischemic stroke were the AGT M235T (p = 0.003), the AGT T174M (p = 0.001), and the AGTR1 A1166C (p = 0.001)." (PMID 38025202, 2023). "We identified that AGTR1 A1166C, AGT M235T, and AGT T174M polymorphisms were associated with an increased risk of ischemic stroke in Mexican young individuals." (PMID 38025202, 2023). "We observed nominal associations of AGT gene expression with the risk of CAD and AF in brain cerebellar hemisphere, ischaemic stroke in brain cerebellum, and T2D in adipose subcutaneous." (PMID 39963705, 2025). "Neuronal overexpression of brain ACE-2 is also neuroprotective in a chronic hypertension mouse model (transgenic for renin and angiotensinogen that overproduces Ang II) following experimental induction of ischaemic stroke." (PMID 27884212, 2016).
osteoporosis (25 papers, 2011 to 2025). A condition of reduced bone mass, with decreased cortical thickness and a decrease in the number and size of the trabeculae of cancellous bone (but normal chemical composition), resulting in increased fracture incidence. "Studies have shown that excessive activation of RAS causes osteoporosis, mainly through an elevation of osteoclastic bone resorption, by using a transgenic mouse model overproducing human renin and angiotensinogen or an infusion of AngII in ovariectomized rats." (PMID 23971050, 2013). "In another study which used a chimeric RAS model of transgenic THM (Tsukuba hypertensive mouse) expressing the human renin and human angiotensinogen genes, a recent study showed that the activation of RAS induces high turnover osteoporosis." (PMID 23971050, 2013).
depression (24 papers, 2013 to 2026). "Mutations of angiotensinogen, AT1Rs, and ACE genes were detected in some patients with depression and schizophrenia." (PMID 35207180, 2022).
Hepatic steatosis (24 papers, 2013 to 2025). Steatosis is a term used to denote lipid accumulation within hepatocytes. "In conclusion, hepatic AGT deficiency downregulated genes related to cell division during the progression of liver steatosis." (PMID 40687776, 2025). "In the present study, we performed two bulk RNA sequencing analyses to explore the molecular basis underlying the inhibition of WD-induced liver steatosis and protective effects of hepatocyte-specific AGT deletion." (PMID 40687776, 2025). "Collectively, our results indicate that hepatocyte-specific AGT deficiency attenuates Western diet-induced liver steatosis." (PMID 31604805, 2019). "In contrast, hepatic AGT deficiency led to ablation of Western diet-induced liver steatosis, as evidenced by both liver triglyceride reduction and hepatic histologic changes." (PMID 31604805, 2019). "Liver steatosis is a typical hepatic manifestation of metabolic disorders; therefore, we next evaluated the effect of hepatocyte-specific AGT deficiency on Western diet-induced liver steatosis." (PMID 31604805, 2019). "Hence, we concluded that hepatic AGT deletion attenuated Western diet-induced liver steatosis and was associated with inhibition of Akt/mTOR/SREBP-1c signaling." (PMID 31604805, 2019). "Thus, our findings implicate that suppression of the SREBP-1c pathway may account for the alleviation of liver steatosis that resulted from hepatocyte-derived AGT deficiency." (PMID 31604805, 2019). "Taken together, it is important to understand the complex interplay between WD, AGT, and hepatocyte proliferation in the pathophysiology of liver steatosis." (PMID 40687776, 2025). "Previous studies determined that hepatocyte-specific deficiency of angiotensinogen (AGT), the unique substrate of the renin-angiotensin system (RAS), alleviates WD-induced hepatic steatosis in mice." (PMID 40687776, 2025). "Patients with NAFLD present elevated ANG II levels, and animals with liver steatosis show increased hepatic expression of AGT, AGT II and ANG II type 1 receptor (AT1R)." (PMID 28505074, 2017). "Our integrated transcriptomic analyses identified five target genes related to cell division that may contribute to the development of liver steatosis mediated by WD and AGT." (PMID 40687776, 2025). "As such, single-cell, single-nuclei, and spatial transcriptomic approaches represent promising tools for future investigations into the relationship between the target genes identified in this study and their potential contributions to AGT-mediated liver steatosis." (PMID 40687776, 2025). "Therefore, it is critical to identify potential molecules driving WD-induced liver steatosis through AGT." (PMID 40687776, 2025). "In the present study, we determined that hepatic AGT could promote Western diet-induced body weight gain and liver steatosis." (PMID 31604805, 2019). "Here, we investigated the role of hepatocyte-derived AGT in liver steatosis." (PMID 31604805, 2019). "Based on these findings, we highlight the key role of hepatocyte-specific AGT in the process of liver steatosis and may provide a novel approach for liver steatosis therapy." (PMID 31604805, 2019). "However, whether AGT deficiency affects diet-induced liver steatosis has not been reported." (PMID 31604805, 2019).
hepatocellular carcinoma (24 papers, 2008 to 2026). A malignant tumor that arises from hepatocytes. "Thus, we demonstrate cyclosporine treatment of human hepatoma cells to significantly reduce DNA-binding of HNF4α to AGT and AGTR1 at gene specific promoters to cause impaired gene expression." (PMID 21298017, 2011). "We focused on AGT in view of its sensor role to the blood glucose and the recognized tumor suppressor function in hepatocellular carcinoma." (PMID 31142626, 2019). "It has been well known that the HNF family is extensively involved in human AGT regulation, for example, HNF-1α and HNF-4 can bind to the AGT promoter sequences and activate AGT expression in human hepatoma cells." (PMID 29053707, 2017). "Transgenic mice expressing human AGT were crossed with a transgenic mouse model of hepatocellular carcinoma." (PMID 25428203, 2014). "VEGF, TGF beta, TNF alpha, PDGF and AGT are all intimately related to the progression of fibrosis to cirrhosis and hepatocellular carcinoma in mammals." (PMID 21901081, 2011). "However, in hepatoma cells, glucose-induced AGT augmentation is mediated predominantly through HNF-1α- and HNF-4-dependent pathways." (PMID 29053707, 2017).
ovarian carcinoma (24 papers, 2006 to 2025). A malignant neoplasm originating from the surface ovarian epithelium. "Ovarian cancer cells can overexpress Ang II as well as stimulate AGT gene expression to generate more Ang II, which can ultimately result in cancer development and MCS formation." (PMID 37891636, 2023). "And AGT was a risk factor for OS in LUAD, ovarian cancer, and melanoma." (PMID 34671200, 2021). "Since there is a significant increase in AGT after ANGII treatment, we hypothesized that ovarian cancer cells directly secrete ANGII enhancing MCS formation and growth, in turn, to increase cancer metastasis in a positive feedback manner." (PMID 30845964, 2019).